STAT3 (signal transducer and activator of transcription 3)
Diseases named in the same sentence as STAT3 in open-access papers (continued):
Sharing a sentence is not in itself a finding about the gene and the disease.
tumor (continued). "The abundance of P. gingivalis and F. nucleatum is significantly elevated in OSCC tissues, and they can promote tumor progression through signaling pathways such as IL-6/STAT3 and E-cadherin/β-catenin." (PMID 41459159, 2025). "Together, these observations strongly suggest that EFNA1 drives tumor progression primarily through activation of the Src/AKT/STAT3 signaling axis." (PMID 39964764, 2025). "While STAT3 is essential for the growth of tumor cells, previous studies have shown that STAT3 is dispensable for the growth of normal cells." (PMID 40118821, 2025). "NSD2 catalyzes STAT3 methylation, which contributes to the activation of the STAT3 pathway and tumor angiogenesis." (PMID 38400589, 2025). "Loss or downregulation of STAT1 is correlated with a poor prognosis, while induction of STAT3 activity also promotes the aggressiveness of the tumor." (PMID 40699751, 2025). "This leads to a reduction in STAT3 levels and the downregulation of Mcl-1 and Bcl-2 protein levels, thereby promoting apoptosis in tumor cells." (PMID 40142963, 2025). "A novel role of tumor-intrinsic PD-L1/JAK/STAT3/IL-6/MDSC axis in both immunosuppression and tumor progression has been recently reported in NSCLC." (PMID 40519900, 2025). "In a mouse model of CRC, tumor-derived G-CSF induces neutrophils to express PD-L1 through the STAT3 pathway, and neutrophils promote tumor by inhibiting anti-tumor immunity of NK cells dependent on PD-L1/PD-1." (PMID 40092983, 2025). "STAT3 additionally regulates metabolic reprogramming supporting tumor growth and metabolic adaptation." (PMID 41373772, 2025). "The NF-κB and STAT3 pathways contribute to a tumor-promoting inflammatory environment by enhancing cell proliferation and survival while inhibiting apoptosis." (PMID 41465474, 2025). "STAT3, activated downstream of IL-6 or tumor-derived cytokines, orchestrates expression of arginase-1, IL-10, and CD163—key mediators of immunosuppressive reprogramming." (PMID 41459539, 2025). "This facilitates nuclear translocation of PKM2, enabling activation of fatty acid synthase (FASN) expression via STAT3 phosphorylation, thereby promoting de novo lipogenesis, tumor proliferation, and vasculogenic mimicry." (PMID 40842995, 2025). "In the TME, IL‐6/JAK/STAT3 signaling promotes tumor cell proliferation, angiogenesis, and metastasis, while strongly suppressing the antitumor immunity." (PMID 41306557, 2025). "This alteration in the downstream signaling pathway introduces epithelial-to-mesenchymal transition and metastatic events in vivo, sufficing earlier findings on the role of canonical STAT3 in tumor suppression." (PMID 41376623, 2025). "Specifically, tumor-derived lactic acid binds the lipid receptor G2A on macrophages, activating STAT3 and promoting TAM polarization." (PMID 40607438, 2025). "In turn, activated CAFs secrete exosomes and soluble factors such as IL-6, CXCL12, and WNT-ligands, which induce JAK/STAT3 signaling in tumor cells and an enhanced PD-L1 expression, supporting immune evasion." (PMID 41439998, 2025). "Knockout of G protein-coupled receptor 68 (GPR68) or inhibition of the IL-6/STAT3 pathway in MSCs has been shown to suppress in situ OS growth and extend the lifespan after tumor xenograft transplantation." (PMID 40600065, 2025). "MDSCs are immunosuppressive cells that hinder T-cell activation and foster tumor growth; the hyperactivation of STAT3 heightens the recruitment and expansion of MDSCs within the TME." (PMID 40881676, 2025). "IL-6 activates the STAT3 signaling pathway in neutrophils, driving their polarization from the N1 phenotype to the N2 phenotype and thereby enhancing their tumor-promoting effects." (PMID 40528159, 2025). "In vivo experiments were performed using tumor-bearing mice treated with STAT3 and HMGB1 inhibitors." (PMID 40389855, 2025). "STAT3 is aberrantly activated in GBM, and IL‐6‐mediated STAT3 activation promotes immune evasion and tumor growth." (PMID 41354084, 2025).
tumor (continued). "Elevated STAT3 expression contributes to tumor development and progression by inhibiting apoptosis in cancer cells." (PMID 40166646, 2025). "S100A4 is a critical component found in HCC exosomes that promoted tumor metastasis by activating STAT3 and inducing osteopontin production." (PMID 40264760, 2025). "Existing literature suggests that IDO1 promotes EMT in BC through the IL-6/STAT3/PD-L1 signaling pathway, enhancing the migratory and invasive potential of tumor cells." (PMID 40287406, 2025). "IL‐6 promotes tumor cell proliferation, survival, and migration by activating the STAT3 signaling pathway." (PMID 40040540, 2025). "The IL-6-dependent phenotype was attributed to protein interactions between STAT3 and stathmin, which stabilize microtubules—a mechanism potentially conserved across various systems, including retinal ganglion cells and tumor cells." (PMID 41514893, 2025). "This phenomenon was further corroborated by respective differences in activation levels of common tumor cell growth pathways STAT3, MAPK/ERK, and AKT in chemoresistant versus chemosensitive HGSOC cells." (PMID 40078282, 2025). "In this study, we initially discovered that inhibiting STAT3 phosphorylation plays a vital role in the anti‐tumor activity of IDET against TNBC." (PMID 40918170, 2025). "The siRNA-mediated depletion of STAT3/Stat3 was effectively triggered, leading to the inhibition of tumor cell proliferation in vitro using the NLP-EXOSOME COMPLEX STAT3-silencer." (PMID 40427146, 2025). "Previous studies have demonstrated that STAT1 and STAT3 can exert opposing effects on tumor development." (PMID 40287766, 2025). "STAT3 is a critical regulator of tumor-supporting neutrophil phenotype, driving their development and immunosuppressive functions." (PMID 40050933, 2025). "Toll-like receptor 9 (TLR9), another key player in immune evasion, upregulates PD-L1 and promotes tumor growth through the PARP1/STAT3 pathway, enhancing tumor cell proliferation, migration, and invasion." (PMID 40486875, 2025). "In PDAC-bearing C57BL/6 mice, curcumin/gelatin NMs also inhibited tumor growth and proliferation while promoting ER stress, further reducing p-STAT3 expression and enhancing Bip expression." (PMID 39861761, 2025). "For example, in some tumor cell studies, STAT3 has been found to bind directly to specific sequence elements in the Cat-B gene promoter and recruit other transcription cofactors, such as histone acetyltransferase (HATs)." (PMID 40948745, 2025). "The interleukin‐6/Janus kinase (JAK)/STAT3 signaling axis is central to STAT3 activation, influencing tumor microenvironment remodeling, angiogenesis, immune evasion, and therapy resistance." (PMID 40166646, 2025). "As a result, M2 macrophages promoted 5-fluorouracil (5-FU) resistance of tumor cells in a mechanism of CCL8 activation of JAK1/STAT3 signaling pathway in tumor cells." (PMID 40361394, 2025). "STAT3 activation reduce tumor cell sensitivity to chemotherapy by regulating the expression of drug transporters, enhancing DNA repair capacity, or influencing apoptosis pathways." (PMID 40909292, 2025). "The increasing focus in cancer immunotherapy has focused attention on the JAK/STAT3 signaling system, which regulates not only tumor development additionally immune evasion and therapeutic response." (PMID 40350446, 2025). "Abnormal stimulation of the JAK2/STAT3/MYC pathway promotes tumor growth, metastasis, and drug resistance." (PMID 40944417, 2025). "Th17 cells contribute to tumor progression as IL-17 triggers IL-6 production, which activates oncogenic signaling pathways, including STAT3." (PMID 41041322, 2025).
tumor (continued). "For example, induction of STAT3 signaling increases tumor glycolysis and proliferation, prevents apoptosis, and promotes drug resistance." (PMID 39905019, 2025). "Supplementing NAD precursors, such as nicotinamide or niacin, can inactivate STAT3 and reverse tumour epithelial–mesenchymal transition (EMT), with effects comparable to those of STAT3 inhibitors." (PMID 39778006, 2025). "Paradoxically,the ample antitumor effects of berberine have an astonishing dose-dependent effect as they markedly suppress the phosphorylation and release of the STAT3 to increase the prevalence of M1 macrophages in tumor microflora." (PMID 41562074, 2025). "Here, in tumor lysates prepared from mice treated for three weeks, levels of demethylated STAT3 decreased in BRAFi + EGFRi relative to vehicle tumors but increased in BRAFi + EGFRi + SP-2577 tumors." (PMID 40264166, 2025). "IL-6 not only promotes the expression of anti-apoptotic proteins such as Bcl-xL and Mcl-1, which help tumor cells resist TNFα-induced apoptosis, but also further drives cell cycle progression by promoting the phosphorylation of STAT3." (PMID 41400642, 2025). "Curcumin can be a molecular target for inhibiting STAT3 in diverse tumor types directly or indirectly via suppression of IL-6 signaling." (PMID 40575656, 2025). "Radiomics analysis of DCE-MRI images in this study offered a non-invasive method for predicting STAT3 expression and characterization of the tumor immune microenvironment." (PMID 40636126, 2025). "This enhanced interaction leads to increased STAT3 and NF-κB activity, thereby promoting tumor cell proliferation through IL-1 and IL-6." (PMID 40562773, 2025). "This widespread STAT3 activity reshapes the immune landscape to favor tumor progression and contributes to the development of cancer cachexia." (PMID 40704145, 2025). "Tumour cell-intrinsic STAT3 induces expression of MHC class I, which hinders the cytotoxic activity of NK cells." (PMID 40407951, 2025). "In STAT3 activation, immunostimulatory molecule production is reduced and their ability to inhibit tumor cell growth is compromised, making it a critical step in TAM induction." (PMID 41294803, 2025). "Given the transcriptomic findings, we next evaluated STAT3 protein levels via immunohistochemistry in baseline tumor tissues from 17 patients treated at other medical centers." (PMID 41446744, 2025). "Given the critical role of STAT3 in cell proliferation in multiple tumor models, we investigated the effect of inhibiting STAT3 activation by WP1066 in OS cells." (PMID 40529368, 2025). "In summary, curcumin, by regulating the STAT3 signaling pathway, not only inhibits tumor growth but also enhances the body’s anti-tumor immune response by remodeling the immune cell composition in the TME." (PMID 40989587, 2025). "Beyond apoptosis, garcinol suppressed metastasis by inhibiting the expression of metalloproteinases (MMPs), enzymes that are involved in tumor resistance, by downregulating miRNAs and attenuating STAT3 and AKT phosphorylation." (PMID 41303402, 2025). "Combination therapies employing immune checkpoint inhibitors and STAT-3 inhibitors present a viable approach to long-term tumor management." (PMID 40227645, 2025). "Upregulated miR-21 is transcriptionally activated by IL-6 via STAT3 and promotes tumorigenesis by targeting the tumor-suppressor PTEN, thereby enhancing PI3K/Akt signaling and sustaining NF-κB activity." (PMID 40943532, 2025). "Our findings are in close agreement with recent studies delineating how in other tumour types the blockade of DDR players hampers the STAT3-dependent transcriptional program." (PMID 41350901, 2025). "Based on these findings, we propose that SLC9A2 inhibits the STAT3 signaling pathway, thereby suppressing metastasis and tumor angiogenesis in CRC." (PMID 40474298, 2025).
tumor (continued). "Nuclear factor-κB (NF-κB) and signal transducer and activator of transcription 3 (STAT3) are key regulators of inflammation, cell transformation, tumor cell survival, proliferation, and metastasis." (PMID 39494324, 2024). "M2-like TAMs were isolated from tumours and characterized ex vivo by western blot analysis of p-STAT3." (PMID 38183060, 2024). "Targeting STAT3 can positively inhibit tumor growth in HNSCC cancer cells, which confirms the belief that STAT3 is an oncogene." (PMID 38474604, 2024). "Inhibition of STAT3 can induce cell apoptosis and is closely related to key processes such as tumor proliferation, survival, and metastasis." (PMID 39056720, 2024). "STAT3 signaling pathway regulates the biogenesis of tumor-derived exosomes contributing to the progress of cancer." (PMID 38725860, 2024). "In the present study, we show that FAK inhibitors stimulate AKT2S128/CCTαS315/319/323-positive CAFs subset to secrete PCs, which induce malignant cells STAT3 activation to facilitate the therapeutic resistance of tumor cells." (PMID 38280862, 2024). "TAMs in advanced breast cancers exhibited preferential FABP4 expression, promoting tumor growth via IL6/STAT3 signaling." (PMID 38185636, 2024). "Immunohistochemical analysis showed that the expression levels of IL-6, IL-6R, and STAT3 in tumor tissue of mice treated with ginsenoside Rh2 were inhibited." (PMID 39845783, 2024). "The phytochemical resveratrol has also demonstrated tumor-suppressive effects by reducing cell viability and inhibiting STAT3 signaling." (PMID 39590345, 2024). "As a response, ccRCC tumor cells stimulate STAT3-mediated transcriptional regulation, directly increasing FGF7 expression at the chromatin level in CAFs." (PMID 39594574, 2024). "Inhibition of SPP1 attenuated N-cadherin and β-catenin expression and the activation of AKT and STAT3 pathway in tumor cells." (PMID 38648200, 2024). "The phosphor-STAT3 staining of untreated HT-29 tumor cells scored approximately 60, compared with 38 in the treated HT-29 group (p < 0.05)." (PMID 38256960, 2024). "Concurrently, STAT3 suppresses pro-inflammatory cytokine production and restricts T cell activation, thereby indirectly fostering tumor progression." (PMID 39519376, 2024). "During tumor formation, hepatitis B virus-encoded X protein (HBx) induced HMGB1 expression, which activates signal transducer and activator of transcription 3 (STAT3) to promote EMT and angiogenesis." (PMID 38725632, 2024). "TNF/STAT3 pathway participates in the regulation of diverse biological processes and ultimately plays a crucial role in tumour formation, metastasis, and drug resistance." (PMID 39586790, 2024). "The hyper-activation of the IL-6/JAK/STAT3 cascade plays a bi-directional role in tumor progression and the related therapeutic strategies to target this pathway failed in a panel of tumor types." (PMID 38274367, 2024). "In the TIM, the IL-6/JAK/STAT3 signaling pathway drives tumor cell proliferation, survival, invasion, and metastasis, while concurrently suppressing anti-tumor immune responses." (PMID 39068665, 2024). "MiR-155-5p in TAMs84 can activate the IL-6R/STAT3/miR-204-5p pathway in colorectal cancer (CRC) to induce tumor chemoresistance by regulating C/EBPβ." (PMID 38341519, 2024). "IL-6-activated STAT3 in turn promotes tumor cell survival by inducing the expression of Bcl-2, survivin, and X-linked inhibitor of apoptosis protein (XIAP), the overexpression of which is related to increased chemoresistance." (PMID 38520006, 2024). "Senescent tumor cells derived IL-6 induced the upregulation of TAMs CD73 expression through the JAK/STAT3 signaling pathway." (PMID 38323313, 2024). "Apart from this, CD39 and CD73 enzymes, which are the downstream targets of STAT3 signaling, coordinately dephosphorylate adenosine triphosphate (ATP) to form adenosine, thus promoting tumor cell metastasis and also angiogenesis." (PMID 38216787, 2024).
tumor (continued). "For instance, STAT3 mediates programmed death-ligand 1 (PD-L1) upregulation by binding directly to the promoter of PD-L1 in tumor cells." (PMID 38339245, 2024). "STAT3 plays a pivotal role in driving tumor-promoting inflammation and evasion of antitumor immunity." (PMID 39113883, 2024). "They successfully delivered siRNA against the oncogene signal transducer and activator of transcription 3 (si-STAT3) to the highly aggressive intracranial GBM tumor via non-invasive systemic administration." (PMID 38059120, 2024). "The signal transducer and activator of transcription 3 (STAT3) is an oncogenic protein, and the STAT3 signaling pathway has a critical role in tumor cell occurrence and development." (PMID 38625901, 2024). "Functional classification of the STAT3-responsive program reveals its major role in tumor maintenance and epithelial homeostasis." (PMID 38573819, 2024). "Overexpression of STAT3 triggers tumorigenesis and provokes tumor development, metastasis, and recurrence of CRC." (PMID 38185635, 2024). "Based on bioinformatics analysis, we found that STAT3 is differently expressed between tumor tissues and normal tissues." (PMID 39132168, 2024). "We further expand on evidence supporting the paradoxical role of STAT3 (as an oncogene or as a tumor suppressor gene) in cancer." (PMID 38339245, 2024). "This suggests that the interaction of RIG-I with STAT3 inhibits the downstream signaling pathway, thereby limiting tumor development." (PMID 39867908, 2024). "At the same time, lncRNA TSLNC8 inhibited the IL-6/STAT3 signaling pathway, inducing tumor suppression." (PMID 39682098, 2024). "Concurrently, studies reveal that radiation enhances PD-L1 expression in tumor cells via the IFN-γ/STAT3 pathway." (PMID 38473415, 2024). "In ccRCC, in vitro experiments have shown that TIM-1 can induce IL-6 expression, thereby activating STAT-3, promoting angiogenesis through the IL-6/STAT-3 pathway, which is conducive to tumour growth and metastasis." (PMID 38831760, 2024). "The combination of curcumin and EGCG downregulates IL-8 expression and inhibits the inflammatory response in the tumor microenvironment of colon cancer by suppressing the JAK/STAT3 signaling pathway." (PMID 39710789, 2024). "The signaling pathways STAT1 and STAT3 are known to play opposing roles in angiogenesis, inflammation and tumor growth." (PMID 39294742, 2024). "This study showed that GMI’s tumor-suppressive action was achieved by blocking IL-6/Stat3 signaling." (PMID 39272862, 2024). "Beyond PDAC, tumour-promoting functions of STAT3 signalling in fibroblasts has also been described in other organs." (PMID 38678021, 2024). "Apart from tumor progression, the STAT3 pathway is also involved in the tumor evasion of the immune system." (PMID 38675144, 2024). "Many tumor immunologists have shown that the cross-talk between STAT3 activation in tumor cells and other cell populations in TME, tightly controls the immune escape and pro-inflammation, thereby facilitating tumor progression." (PMID 38245798, 2024). "Conclusions: miR-125a-5p functions as a tumor suppressor in PCa by targeting STAT3, thereby inducing autophagy and apoptosis." (PMID 39132168, 2024). "In STAT3 signaling, Shp1 directly dephosphorylates the Tyr705 phosphorylation site on STAT3 and as such, has been harnessed as a strategy for modulating STAT3 activity with the aim of inhibiting tumor growth and preventing development of therapy resistance." (PMID 38339245, 2024).